EGFR (epidermal growth factor receptor)
Diseases named in the same sentence as EGFR in open-access papers (continued):
Sharing a sentence is not in itself a finding about the gene and the disease.
lung adenocarcinoma (continued). "K-Ras and EGFR is frequently activated by mutation and they are mutually exclusive in lung adenocarcinomas, and these oncogenes might act as upstream regulator of C/EBPβ." (PMID 30754676, 2019). "Here, we evaluated clonal status, which may reflect intratumoral heterogeneity, in lung adenocarcinoma with EGFR-TKI sensitizing mutation (mEGFR) and its clinical implications." (PMID 31632498, 2019). "EGFR-TKI treatment decreases glycolysis metabolism in lung adenocarcinoma harbor EGFR mutations." (PMID 31444368, 2019). "To confirm the clinical relevance of this finding, we extracted 740 lung adenocarcinoma from TCGA database, among which 54 patients were confirmed with EGFR activating mutation (n = 25), FGFR1/2 amplification (n = 15), MET amplification (n = 12), or RET fusion (n = 2)." (PMID 31221965, 2019). "One patient in our group with an EGFR mutation in exon 19 (p.746-750del) showed the acinar subtype, which conformed to the morphological features, and the mutation was in concordance with that of the primary lung adenocarcinoma." (PMID 31455365, 2019). "We investigated the significance of MUC21 in EGFR-mutated lung adenocarcinoma (LADC)." (PMID 30973916, 2019). "However, the EGFR mutation frequencies in East Asian lung adenocarcinoma were higher than previously reported in USA/Europe patients, whereas the overall frequency of KRAS mutations was much lower than in the West instead." (PMID 31749831, 2019). "There have been different reported incidences of EGFR mutations in lung adenocarcinomas around, depending on ethnicity, reported to be 40% in East Asia, 15% in Europe, 22% in North America, 26% in the Indian subconti- nent, 36% in South America, 12% in Oceania and 21% in Africa." (PMID 31531095, 2019). "Therefore, this study evaluated the feasibility of single-cell analysis of EGFR L858R mutation using H1975 cells, to detect the presence of intratumoral heterogeneity in lung adenocarcinoma." (PMID 31014278, 2019). "Moreover, loss of NF1 expression has been observed in lung adenocarcinomas and melanomas that are resistant to treatment with EGFR and BRAF inhibitors, respectively." (PMID 30858928, 2019). "Therefore, we need a non-invasive and accurate method to distinguish EGFR mutation status of the metastatic lesions throughout the treatment process of lung adenocarcinoma." (PMID 31174617, 2019). "However, tumor progression often occurs via the emergence of the EGFR T790 M resistance mutation during the treatment of EGFR-mutant lung adenocarcinomas patients with first-generation EGFR tyrosine kinase inhibitors (TKIs; Erlotinib, Gefitinib)." (PMID 30709379, 2019). "In non‐Asian cohorts, EGFR mutation frequencies of 10%–30% are described in lung adenocarcinomas." (PMID 31668020, 2019). "Therefore recent guidelines suggest that EGFR mo- lecular testing and mutation analysis should be performed in all patients with lung adenocarcinoma." (PMID 31531095, 2019). "Correlation between MUC21 expression and pathological factors in EGFR-mutated lung adenocarcinomas." (PMID 30973916, 2019). "It has been shown that a subset of patients with lung adenocarcinoma (10 to 40%) have specific active EGFR mutations, mostly in exons 18 to 21, that are associated with increased sensitivity to tyrosine-kinase inhibitors (TKIs) such as gefitinib (Iressa) or erlotinib (Tarceva)." (PMID 31531095, 2019). "We also focused on PD-L1 expression in patients with EGFR mutated lung adenocarcinomas." (PMID 31561631, 2019). "We hypothesized that DESCT features can be used to distinguish KRAS mutations from EGFR mutations in lung adenocarcinoma." (PMID 31783917, 2019). "EGFR mutations are routinely explored in lung adenocarcinoma by sequencing tumoral DNA." (PMID 30612556, 2019).
lung adenocarcinoma (continued). "We then compared diagnostic sensitivity of MSI and ADx-amplification refractory mutation system (ARMS) for the detection of EGFR mutation in pathological confirmed lung adenocarcinoma (AC) and explored EGFR mutations associated biomarkers to depict EGFR spatial distribution base on ambient MSI." (PMID 31555581, 2019). "Our data showed that KRAS mutations are the most common genetic alterations in Sardinian patients with lung adenocarcinoma, involving 22.1% of the cases examined and being mutually exclusive with the EGFR mutations, which were found in 12.6% of the cases studied." (PMID 31711449, 2019). "In this study, we found that Del19 mutations triggered significant higher antibody responses as compared to EGFR L858 point mtations in Chinese lung adenocarcinoma patients, suggesting that Del19 mutations of EGFR are expressed at protein level and immunogenic." (PMID 31722672, 2019). "Support to this hypothesis comes from the recent observation of a higher incidence of EGFR mutations in well and moderately differentiated lung adenocarcinomas, likely as a reflection of lower TMB associated with presence of a single driver mutation." (PMID 30728907, 2019). "Since the serum cross-reactivity to wild type EGFR protein may reflect the immunogenicity of mutant EGFRs, we compared the antibody responses in lung adenocarcinoma patients with EGFR Del19 as that with EGFR L858R point mutation." (PMID 31722672, 2019). "Based on the single-cell method, we explored whether EGFR activating mutation heterogeneity in a tumor did exist in actual lung adenocarcinoma specimens positive for the L858R mutation in exon 21 of EGFR and its relation to EGFR-TKI response." (PMID 31014278, 2019). "The mucus produced in KRAS mutation lung adenocarcinoma and the rich blood supply of EGFR mutation lung adenocarcinoma may result in the lower quantitative value with KRAS mutations compared to EGFR mutations." (PMID 31783917, 2019). "The activation of EGFR mutations can be detected by use of image features for the stratification of patients in terms of their responses to tyrosine kinase inhibitors (TKIs) therapy for lung adenocarcinomas." (PMID 30247662, 2019). "CT imaging-based histogram features might contribute to the diagnosis and prediction of EGFR mutation status of bone metastases in patients with primary lung adenocarcinoma." (PMID 31174617, 2019). "This might explain why TTF-1 positivity has a more significant prognostic impact than the EGFR mutation status among patients with advanced lung adenocarcinoma in the EGFR-TKI era." (PMID 31196060, 2019). "In conclusion, our data demonstrate that CSF shunting may effectively control intracranial hypertension due to LM-H from lung adenocarcinoma in patients with an EGFR mutation, especially for patients with a good ECOG PS and controlled extracranial cancer." (PMID 30629621, 2019). "The immunogenicity of EGFR Del19 mutations, frequent in Chinese lung adenocarcinoma patients, remains unclear." (PMID 31722672, 2019). "Therefore, we aimed to retrospectively explore potential differences in DESCT features between KRAS and EGFR mutations in a cohort of Chinese patients with lung adenocarcinomas." (PMID 31783917, 2019). "Our study suggested the intratumoral heterogeneity of EGFR-activating mutations in lung adenocarcinoma confirmed on the single-cell level, which might be associated with EGFR-TKIs response in lung adenocarcinoma patients harboring the EGFR L858R mutation." (PMID 31014278, 2019). "We evaluated whether the optimal selection of CT reconstruction settings enables the construction of a radiomics model to predict epidermal growth factor receptor (EGFR) mutation status in primary lung adenocarcinoma (LAC) using standard of care CT images." (PMID 30559455, 2018). "Meanwhile, half of the lung adenocarcinoma patients in Asia are accompanied with EGFR mutation." (PMID 29472856, 2018).
lung adenocarcinoma (continued). "In this study, we demonstrated that the optimal selection of reconstruction parameters on CT-scan could enhance the predictive value of a radiomics signature to identify EGFR mutation status in early-stage lung adenocarcinoma." (PMID 30559455, 2018). "Lung adenocarcinomas harboring oncogenic driver mutations at the level of EGFR and ROS1 and ALK rearrangements have a lower mutational load, often occur in never smokers and are sensitive to targeting with specific inhibitors and this offered new therapeutic perspectives for these patients." (PMID 30060526, 2018). "However, no study has performed integrative analysis to investigate the complex miRNA–mRNA network in EGFR-mutated lung adenocarcinoma." (PMID 30404194, 2018). "As is reported, half of the lung adenocarcinoma patients were accompanied with an EGFR mutation." (PMID 29472856, 2018). "For example, EGFR G719C is a well-known actionable mutation in patients with lung adenocarcinoma, and patients with FGFR W290C mutation-positive tumor were reported to be sensitive to FGFR inhibitors, but these mutations were determined as VUSs by WfG ver.27 (false negative examples)." (PMID 30474028, 2018). "The H1975 cell line is derived from a human lung adenocarcinoma and has the oncogenic EGFR tyrosine kinase activating mutation L858R as well as the T790M mutation that makes it resistant to first-generation EGFR tyrosine kinase inhibitors (TKIs) such as gefitinib and erlotinib." (PMID 29779406, 2018). "Therefore, the present study focused on the role of MPV in EGFR mutation positive lung adenocarcinoma who received EGFR-TKI." (PMID 30192878, 2018). "In addition, previous study show that low expression of NF1 was associated with primary and acquired resistance of lung adenocarcinomas to EGFR‐TKIs in patients." (PMID 29493886, 2018). "The aim of this study is to assess whether radiomic features using CT texture analysis can identify lung adenocarcinomas with EGFR exon 19 mutation and 21 mutation." (PMID 30547844, 2018). "Therefore, acknowledge of EGFR mutation status of lung adenocarcinomas is essential for personalized therapy." (PMID 30547844, 2018). "In summary, we identified the unique miRNA–mRNA interactions in EGFR-mutated lung adenocarcinoma." (PMID 30404194, 2018). "Interestingly, lung adenocarcinomas associated with specific driver mutations, such as EGFR, ALK or ROS1 display a specific pattern of CpGs methylation." (PMID 30060526, 2018). "A separate analysis of EGFR exon 19 and 21 mutations may facilitate personalized treatment of lung adenocarcinomas." (PMID 30547844, 2018). "Several radiomic features are associated with EGFR mutation statuses of lung adenocarcinoma." (PMID 30547844, 2018). "CSD is an important predictive and prognostic factor in patients with EGFR-mutated lung adenocarcinoma, and associated smoking-related gene signatures might affect the outcomes." (PMID 30055587, 2018). "Lung adenocarcinoma may arise from an accumulation of genetic mutations, of which those in epidermal growth factor receptor (EGFR) are some of the most important and are associated with tumour progression, proliferation, and survival." (PMID 29849818, 2018). "Indeed, we detected EGFR mutations in 38.4% of our cohort, which was in line with previous surveys of stage I lung adenocarcinoma, but slightly lower than the rate in another report." (PMID 29849818, 2018). "Therefore, the purpose of this study was to retrospectively identify CT features that correlate with EGFR mutation status in lung adenocarcinomas in a cohort of East Asian patients." (PMID 28988295, 2018). "However, there were no remarkable differences in Notch1 mRNA expression in either peripheral or BALF CD4+ T cells between EGFR mutation and non-EGFR mutation lung adenocarcinoma patients (P=0.852 and 0.403, respectively)." (PMID 30473538, 2018). "EGFR-mutated lung adenocarcinoma is orchestrated by complex miRNA–mRNA interactions." (PMID 30404194, 2018).
lung adenocarcinoma (continued). "Patients with advanced lung adenocarcinoma harboring epidermal growth factor receptor (EGFR)-activating mutations have good response rate and longer progression-free survival (PFS) when treated with the tyrosine kinase inhibitors (TKI) compared with platinum-based chemotherapy." (PMID 29849936, 2018). "Additionally, the mTOR pathway is associated with induction of MMP-1 expression in lung adenocarcinoma, including EGFR-TKI–resistant cells." (PMID 29463039, 2018). "Overall, our phase IV clinical trial demonstrated that the companion diagnostic method could identify lung adenocarcinoma patients with activating EGFR mutation with a frequency that was found in other Caucasian patient populations." (PMID 29801465, 2018). "Therefore, 9 patients with EGFR mutation lung adenocarcinoma and having clinical resistance to an EGFR TKI underwent repeat biopsy for tumor genotyping by cryoprobe biopsy during semirigid pleuroscopy." (PMID 29610630, 2018). "In the study, we showed the clinical relevance of S100A9+ MDSCs and TAMs in terms of microenvironment-mediated resistance to EGFR-TKIs in the setting of lung adenocarcinoma harboring activating EGFR mutations and linked the circulating S100A9+ MDSCs to tumor microenvironment." (PMID 29484139, 2018). "However, most of this progress has been made in lung adenocarcinoma, through the identification of mutations of the epidermal growth factor receptor (EGFR), EML4-ALK fusions, and other driver alterations that are highly sensitive to targeted drug therapy." (PMID 29581842, 2018). "The prevalence of EGFR mutations in lung adenocarcinomas differs by patient ancestry." (PMID 29554880, 2018). "To conclude, this study is the first to reveal that MMP-1 plays an important role in the migration and invasion abilities of EGFR-TKI–resistant lung adenocarcinoma cells, and the mTOR pathway is associated with the induction of MMP-1 expression in these cells, resulting in a poor prognosis." (PMID 29463039, 2018). "The tumor specimen was also examined as an advanced primary lung adenocarcinoma and assessed for the following tumor markers: epidermal growth factor receptor (EGFR) mutation, anaplastic lymphoma kinase (ALK) rearrangement, ROS1 rearrangement, and programmed death-ligand 1 (PD-L1) expression." (PMID 30443294, 2018). "In conclusion, this is the first study to identify that elderly patients with stage IV lung adenocarcinoma harboring uncommon EGFR mutation might have a longer PFS." (PMID 30428509, 2018). "Our findings, if validated, would identify a list of miRNA–mRNA interactions that could be used to understand the molecular pathogenesis of EGFR-mutated lung adenocarcinoma." (PMID 30404194, 2018). "However, the predictive value of EGFR mutations in patients with pathological T1 lung adenocarcinoma is still unclear." (PMID 29849818, 2018). "Tyrosine kinase inhibitors (TKIs, erlotinib or gefitinib) have been prescribed in lung adenocarcinoma patients who have epidermal growth factor receptor (EGFR) mutations and have markedly improved the survival outcome, but patients still eventually develop TKI resistance." (PMID 29950164, 2018). "Epidermal growth factor receptor mutations occur in ~10–25% of lung adenocarcinoma patients and these patients benefit, at least initially, from neutralizing treatment with mAbs (e.g., cetuximab and necitumumab) and from TKI (e.g., erlotinib, gefitinib, and afatinib)." (PMID 30087852, 2018). "Patients with lung adenocarcinoma whose tumor harbor specific gene mutations, such as epidermal growth factor receptor (EGFR) mutation or anaplastic lymphoma kinase (ALK) fusion, derive significant benefit from targeted agents, tyrosine kinase inhibitors (TKIs), and have better prognosis." (PMID 30509312, 2018).
lung adenocarcinoma (continued). "The identification of EGFR mutations and the discovery of their exquisite sensitivity to epidermal growth factor receptor (EGFR) inhibitors dramatically changed the therapeutic routine for lung adenocarcinoma (LADC) patients." (PMID 30405134, 2018). "Hence, the purpose of this study was to investigate EGFR mutations in the context of carcinoembryonic antigen levels and to assess the prognostic value of such mutations in patients with pathological T1 lung adenocarcinoma." (PMID 29849818, 2018). "Whether the combination of PD‐L1 with EGFR‐TKI has a more obvious effect on lung adenocarcinoma patients with EGFR mutations, it is our future direction of study in this field." (PMID 29726585, 2018). "In addition, VEGF expression was found to be upregulated in EGFR-mutated lung adenocarcinomas which additionally increases cell survival via activation of AKT and STAT5 pathways." (PMID 30087852, 2018). "In this report, we correlated S100A9+ MDSCs and TAMs to EGFR-TKI treatment response in patients with EGFR mutated lung adenocarcinoma and addressed the question as to whether this MDSC is a source of TAMs." (PMID 29484139, 2018). "Drug resistance is common in the treatment of molecular-targeted drugs; for example, T790M mutation of EGFR in lung adenocarcinoma was the major cause of gefitinib resistance and other TKI drugs’ resistance, while K-Ras mutation was the main cause of cetuximab resistance in colorectal cancer." (PMID 29973197, 2018). "The scoring system including the CT imaging features of lung adenocarcinomas in combination with clinical variables may prove to be useful in prognosticating EGFR mutation subtypes." (PMID 30235778, 2018). "Similarly, our mRNA expression signature in EGFR-mutated tumors included DUSP4, EGFR, TNFRSF10B, and LRRC3, all reportedly deregulated in EGFR-mutated lung adenocarcinoma." (PMID 30404194, 2018). "The first targeted therapy was developed for the treatment of EGFR-mutated lung adenocarcinomas." (PMID 30060526, 2018). "The aim of this study is to investigate the protein expression level of Nrf2 and Keap1 in lung adenocarcinoma and to elucidate the correlation between Nrf2 or Keap1 expression and the status of EGFR gene mutation and to determine the effects of Nrf2 and Keap1 on the patients." (PMID 29587953, 2018). "Based on the report indicating that the heterogeneous distribution of EGFR mutations is extremely rare in lung adenocarcinoma, we used the EGFR mutation status determined from primary or metastatic lung cancer specimens as a surrogate of the entire eligible population." (PMID 28881820, 2017). "Interestingly, lung adenocarcinomas with EGFR TKI—sensitive mutations expressed high levels of SORT1." (PMID 29084952, 2017). "Moreover, somatic-activating mutations in EGFR resulted in STAT3 over-activation through IL-6 production in human lung adenocarcinomas." (PMID 27861147, 2017). "We demonstrated that in patients with stage IV lung adenocarcinoma harboring susceptible EGFR mutations, an initial dose of 30 mg daily of afatinib may not be inferior to 40 mg daily with regards to response rate, PFS, and OS." (PMID 29237484, 2017). "We also evaluated PFS and overall survival (OS) according to EGFR mutation type (exon 19 deletion and exon 21 L858R) because they constitute ~90% of all EGFR mutation-positive lung adenocarcinomas, and are strongly associated with robust responses to EGFR-TKIs." (PMID 28168310, 2017). "Prognoses of lung adenocarcinoma patients with BMs are often associated with gene mutation status, including mutations in the epidermal growth factor receptor (EGFR), anaplastic lymphoma kinase-rearranged (ALK), and V-Ki-ras2 Kirsten rat sarcoma viral oncogene homolog (kRAS)." (PMID 29050314, 2017).